SF3B1 (splicing factor 3b subunit 1)
Diseases named in the same sentence as SF3B1 in open-access papers (continued):
Sharing a sentence is not in itself a finding about the gene and the disease.
tumor (166 papers, 2012 to 2026). "Considering that lactotroph PitNETs associate with somatic hotspot SF3B1 mutations, tumor DNAs (tDNA) from 6 and cDNAs from 22 TrkAIII RT-PCR positive lactotroph PitNETs were evaluated for the presence of hotspot SF3B1 c.1866 G > T; c." (PMID 38534441, 2024). "Splicing factors mutations are particularly prevalent in myeloid neoplasms; for example, SF3B1, that increases anti-apoptotic isoforms, enhances tumor proliferation and progression, and is associated with poor survival of patients." (PMID 39845971, 2024). "About half of MDS tumor samples have mutations in spliceosome genes, with SF3B1 being the most commonly mutated one." (PMID 39303038, 2024). "SF3B1 mutations are known to contribute to tumor pathogenesis by disrupting various cellular functions and pathways, including heme biosynthesis, mitochondrial metabolism, and the NF-κB pathway." (PMID 40729294, 2024). "In line with the earlier findings, SF3B1 variants were associated with a larger tumor size and increased mortality, but also with a higher Ki67 index and a need for more therapeutic interventions." (PMID 38067388, 2023). "For example, mutated SF3B1 (a splicing factor in the spliceosome) in uveal melanoma generates tumor-specific neoantigens that activate specific CD8+ T cells to kill tumor cells." (PMID 36604431, 2023). "SF3B1 hotspot mutations are associated with a poor prognosis in several tumor types and lead to global disruption of canonical splicing." (PMID 37524790, 2023). "A recent study exerted intron splicing events generated by SF3B1 mutations that are specific to tumor patients to design synthetic introns and achieve targeted clearance of tumor cells." (PMID 38067392, 2023). "One of these genes is SF3B1, for which hotspot mutations occur in various tumor types, including PDAC." (PMID 37823551, 2023). "e.g., if cytogenetic, genetic or epigenetic changes associated with a more favorable prognosis such as disomy 3, or mutations in EIF1AX or SF3B1 are relatively more common in the north -even though tumor dimensions are similar." (PMID 36310339, 2022). "Noticeably, the clinical outcome of these double-mutated cases in this study was very poor, with a median survival more in keeping with that of patients with PHF6-mutated neoplasms than that of SF3B1-mutated neoplasms." (PMID 36671709, 2022). "Neoepitopes derived from SF3B1R625-related junctions have been found in tumor cells expressing mutated SF3B1, other than cells with wild-type SF3B1." (PMID 36384590, 2022). "Taken together, these data suggest that tumor-associated mutations in SF3B1 induce a BRCA-like cellular phenotype that confers synthetic lethality to DNA-damaging agents and PARP inhibitors, which can be exploited therapeutically." (PMID 35027467, 2022). "Taken together, our data demonstrate that the common tumor-associated mutation in SF3B1, K700E, recapitulates many of the cellular deficits that are characteristic of loss of BRCA1/2." (PMID 35027467, 2022). "We identified 23 neoplasms that had mutations in both SF3B1 and PHF6, representing 0.4% of all neoplasms assessed." (PMID 36671709, 2022). "To determine the mechanism by which SF3B1 mutation promotes tumor growth in PDAC, we performed gene set enrichment analysis by utilizing RNA sequencing data from TCGA." (PMID 33932092, 2021). "In this study, we revealed a tumor‐promoting role of SF3B1 mutation in PDAC cells via loss‐of‐function and gain‐of‐function studies." (PMID 33932092, 2021). "SF3B1 mutations were almost always mutually exclusive of the presence of BAP1 alteration in tumor specimens except one specimen." (PMID 34830903, 2021). "Collectively, these findings suggest that the SF3B1 mutation is critically involved in cell proliferation and tumor growth of PDAC." (PMID 33932092, 2021). "Of the patients who had a solitary metastasis (n = 18), 11 originated from a primary BAP1-mutated tumors and one from a primary SF3B1-mutated tumor." (PMID 34771480, 2021).
tumor (continued). "Of the patients who had a miliary metastasis pattern (n = 24), 17 had a primary BAP1-mutated tumor and two had a primary SF3B1-mutated tumor." (PMID 34771480, 2021). "Of the patients who had a solitary metastasis (n = 18), 11 had an aberrant BAP1 tumor and one with an SF3B1-mutated tumor." (PMID 34771480, 2021). "EIF1AX and SF3B1 mutations occur especially in low-risk D3 tumours, while BAP1 mutations are observed in most high-risk M3 UM." (PMID 34439175, 2021). "To assess the impact of the underlying genetic mutations on the risk of metastasis, we assessed BAP1- and SF3B1-mutations in patients with available tumor tissue." (PMID 34830810, 2021). "Of the patients who had a miliary metastasis pattern (n = 24), 17 had an aberrant BAP1 tumor and two had an SF3B1-mutated tumor." (PMID 34771480, 2021). "EIF1AX mutations are associated with a good prognostic outcome; tumours with an SF3B1 mutation lead to an intermediate prognosis, in contrast to UMs with a BAP1 mutation." (PMID 32998469, 2020). "In particular, we discuss the functional consequences of SF3B1 mutation in tumors, with multiple roles in tumor pathogenesis, aberrant splicing events, and changes in sensitivity to SF3B small-molecule inhibitors." (PMID 32905346, 2020). "SF3B1 mutations were present in 15 tumours, the majority occurring in category 2, in line with other studies." (PMID 32415113, 2020). "Upon analyzing published RNA-seq raw data, we found that SF3B1 was aberrantly spliced in various neoplasms carrying an SF3B1 mutation, including in MDS-RS." (PMID 32168916, 2020). "We found that SF3B1 was aberrantly spliced in various neoplasms carrying an SF3B1 mutation, by exploring publicly available RNA sequencing raw data." (PMID 32168916, 2020). "The SF3B1 mutation was found in both the first tumour biopsy sample (disease which remained quiescent for 13 years) and the recurrent tumour sample." (PMID 30558566, 2018). "The presence of the SF3B1 mutation was confirmed in both the primary and recurrent tumour of this individual." (PMID 30558566, 2018). "An SF3B1 mutation can cause abnormal pre-RNA splicing that can lead to tumorigenesis, tumor drug resistance, or others detrimental features." (PMID 29383138, 2017). "In conclusion, our findings indicate that JA evokes tumor-specific activity by targeting SF3B1 and causing abnormal splicing patterns, in addition to its previously reported activity of inhibiting microtubule polymerization." (PMID 28198434, 2017). "The majority of these cryptic 3’SSs were observed in all three tumor types despite the divergent clinical implications of SF3B1 mutation." (PMID 25768983, 2015). "This SF3B1 inhibition could potentially cause an SF3B1-mutated tumour to become less aggressive in nature through defective RNA transcript production and subsequent nonsense-mediated decay activation." (PMID 40361330, 2025). "SF3B1 mutations play a multifaceted role in tumor pathogenesis." (PMID 40158006, 2025). "Furthermore, mutations in SF3B1 in UM tumors lead to changes in splicing that produce tumor neoepitopes restricted to MHC class I, which are recognized by the patient’s CD8+ T-cells." (PMID 38920653, 2024). "Finally, in patient #26, a SNP in SF3B1 reported with an 11% variant frequency in the patient’s primary tumor biopsy was identified in the matched CTC culture, CDX, and CDX metastases." (PMID 36980717, 2023). "One is that BP selection is altered in cancerous cells carrying recurrent mutations in SF3B1 that influence tumor progression, and the other is that bacteria produce small molecule splicing inhibitors (Spliceostatin-A, Pladienolide-B, etc.)that block loading of the branch point in to SF3B1." (PMID 37873484, 2023).
tumor (continued). "The significance of SF3B1 variants for clinical prognosis in neoplasms remains unclear, but they could represent a druggable target." (PMID 38067388, 2023). "In addition, somatic BAP1 mutation was found in 3 tumors (18.8%) and 1 tumor (6.2%) had a SF3B1 mutation." (PMID 35267470, 2022). "In the SIRT group, one tumor of a patient presented with SF3B1 mutation besides GNAQ mutation." (PMID 35267470, 2022). "Despite the high frequency of SF3B1 mutations, the functional impact of these on tumor development remains unknown." (PMID 35027467, 2022). "We hypothesize that the tumor-specific splice isoforms associated with SF3B1 mutations may act as antigens enabling better immune control of the tumors." (PMID 34031440, 2021). "These pathways indicate that SF3B1 mutation may contribute to cell cycle progression and tumor glucose metabolism." (PMID 33932092, 2021). "SF3B1 mutations play different roles in the biological processes of different tumor types." (PMID 33932092, 2021). "Interestingly, accessible data from the PanCancer study (TCGA) demonstrated that SF3B1 expression levels were directly associated with neoplasm disease stage, being most expressed in poorly differentiated tumors." (PMID 34857016, 2021). "Taken together, aberrant PPP2R5A splicing induced by SF3B1 mutation might contribute to c‐Myc activation and subsequent glycolytic metabolism and tumor growth." (PMID 33932092, 2021). "The high mutation rate of SF3B1 in hematological tumors strongly suggests its tumor‐driving effect." (PMID 33932092, 2021). "SF3B1 is the most frequently mutated splicing factor in tumours." (PMID 29796170, 2018). "Collectively, XC24 antibody was revealed as a tumor-associated antibody against SF3B1." (PMID 29954402, 2018). "Interestingly, we found several tumor suppressor miRNAs to be downregulated in patient samples with SF3B1 and SRSF2 mutations." (PMID 26848861, 2016). "Recently, RNA-sequencing (RNA-Seq) analysis of CLL, breast cancer and UM showed that a global splicing defect in SF3B1-mutated tumours consists in usage of cryptic 3′ss (hereafter called AG′) located 10 to 30 bases upstream of normal 3′ss, yet the underlying mechanism has remained poorly understood." (PMID 26842708, 2016). "SF3B1 mutations were found in 16 tumours affecting two hotspots p.R625 and p.K666." (PMID 26842708, 2016). "SF3B1mut often undergoes aberrant activation of the DNA damage response due to mis‐spliced proteins, thus existing DNA damaging agents (e.g., etoposide) or synthetic lethal small molecule inhibitors (e.g., PARP inhibitors) could preferentially target tumor cells carrying SF3B1 mutation." (PMID 40124717, 2025). "Therefore, we hypothesized that SF3B1 mutation-induced immune and inflammatory disorders causing tumor susceptibility may also cause AF development." (PMID 39170695, 2024). "Thus, it is possible that other genetic or epigenetic alterations might help cells bypass senescence associated with the combined mutations of BAP1 and SF3B1, leading to the co‐existing mutations of these two genes in rare tumor cases." (PMID 34706158, 2022). "Finally, CLL samples with mutations in NOTCH1 and SF3B1 show a distinct DNA methylation pattern, which suggests interplay between the most frequent genomic events and the epigenetic reprogramming associated with this neoplasia." (PMID 23656622, 2013). "Since the therapeutic targeting of this protein might provide novel strategies for the treatment of a large number of CLL patients with a disease resistant to existing drugs, further studies aimed at determining the exact mechanism that connects SF3B1 mutation to tumor development are warranted." (PMID 23656622, 2013). "SF3B1-mutant tumours often present with additional copies of chromosome 8q and are associated with an intermediate prognosis with relatively late metastases." (PMID 40240901, 2025).
tumor (continued). "Prognostically-relevant molecular tumour subtypes can be distinguished based on the presence of additional drivers: a so-called ‘BSE mutation’ in BAP1, SF3B1 or EIF1AX and copy number alterations (CNAs) affecting chromosome 3p or 8q." (PMID 40240901, 2025). "The splicing factor SF3B1 is highly expressed in endometrial tissues, and SF3B1 silencing impaired the proliferation, migration and invasion abilities of tumor cells." (PMID 39910288, 2025). "Still, additional mutations in BAP1, SF3B1 and EIF1AX were detected in 15/17 samples and chromosome 3p and 8q copy numbers matched the primary tumour in 19/21 and 18/20 samples, respectively." (PMID 40240901, 2025). "SF3B1 mutations were associated with Class 1 tumors (p < 0.0001), PRAME(+) status (p < 0.0001), decreased patient age (p < 0.0001), increased tumor diameter (p = 0.02), and brown iris color (p = 0.008)." (PMID 41387680, 2025). "Based on the known mutational status of the respective primary tumours, EIF1AX mutations were successfully identified in 6/6 vitreous fluid samples, SF3B1 mutations in 6/8 samples and BAP1 mutations in 5/5 samples." (PMID 40240901, 2025). "Previous studies have found a close association between SF3B1 and EIF1AX gene mutations and tumor metastasis, with most UVM patients with SF3B1 mutations eventually developing metastasis." (PMID 40703526, 2025). "Our research study has identified four ligands exhibiting molecular features that hold promise in regulating SF3B1 activity within MDS and potentially other neoplasms associated with the SF3B1 K700E mutation." (PMID 38975181, 2024). "Our research has implications for the development of SF3B1 inhibitors such as PlaB that show potent anti-tumour activity in vitro and in vivo." (PMID 38884273, 2024). "Phosphorylation is critical for the association of SF3B1 with U5 and U6 snRNAs in activated spliceosomes; therefore, inhibiting SF3B1 phosphorylation is a novel direction for tumor therapy." (PMID 38462618, 2024). "We induced global inhibition of splicing in Huh7 human hepatocellular carcinoma cells, in which miR-122 is highly expressed, using the small molecule anti-tumour compound pladienolide B (PlaB), an inhibitor of the SF3B1 component of the U2 snRNP." (PMID 38884273, 2024). "To investigate the impact of SF3B1 mutation on splicing in CLL, we first used RNA-seq data from tumor B cells from 298 patients diagnosed with CLL from the International Cancer Genome Consortium (ICGC) and B cell samples from four healthy donors." (PMID 37562845, 2023). "The SF3B1 residues involved in neoplasia are crucial for maintaining the tertiary structure of the protein." (PMID 38067388, 2023). "Several recent studies have evaluated the mechanistic contribution of genes misspliced by oncogenic SF3B1 to tumor progression." (PMID 37823551, 2023). "In this study, U2AF1, DNMT3A, SF3B1, and EZH2 in the secondary tumor group was higher than that in the tumor‐free group, while the mutation rate of ASXL1, TET2, and KMT2D was higher in the tumor‐free group." (PMID 36727544, 2023). "BCL2-like 2 (BCL2L2) was found as a key link regulated through splicing regulation by SF3B1, and mitochondrial DNA (mtDNA) released from tumor cells with pyroptosis played a crucial part in polarization of macrophages and infiltration of cytotoxic lymphocytes." (PMID 38012150, 2023). "In the positive ion mode, F1-scores were 0.65, 0.35, and 0.64 for patients harboring a BAP1, SF3B1, and EIF1AX-mutated tumor, respectively." (PMID 36982149, 2023). "Upon inhibition of SF3B1 using pladienolide B, there was a significant increase in the number of neutrophils and macrophages per mg of tumor tissue (p < 0.05)." (PMID 38012150, 2023). "Capitalizing on the oncogenic properties of SF3B1 and its potential for suppressing tumor growth through blockade or silencing, several drugs have been developed to target SF3B1." (PMID 37875914, 2023).
tumor (continued). "Sf3b1 overexpression was also corroborated in tumor samples from EPed mouse model vs. control samples from neural precursors." (PMID 35086552, 2022). "ROC-curve analyses also supported the capacity of Sf3b1 levels to discriminate between tumor vs. control samples, showing an AUC of 0.96." (PMID 35086552, 2022). "These analyses unveil SF3B1 as a potential biomarker being a novel pharmacological target in this devastating tumor." (PMID 35086552, 2022). "Here, we review the current knowledge about the genetic characteristics of U1 snRNA, SF3B1, and U2AF1 somatic mutations and the mechanism by which they influence splicing decision and, as a consequence, tumor development." (PMID 35053445, 2022). "In recent years, recurrent hotspot mutations in the spliceosome components U1 snRNA, SF3B1, and U2AF1 have been identified across different tumor types." (PMID 35053445, 2022). "Consistent with the mRNA results, IHC analyses of FFPE samples from our patient cohort revealed that nuclear SF3B1 protein levels were significantly elevated in GBM samples vs. non-tumor FFPE -samples." (PMID 35086552, 2022). "Mutations in the splice factor SF3B1/SAP155 affects the formation of BRD9 in the ncBAF complex and this changes transcriptional output and promotes tumour growth." (PMID 35187582, 2022). "To gain an understanding of the role of SF3B1 in tumor growth, we aimed to characterize SF3B1-regulated splicing events." (PMID 35061527, 2022). "Our results suggested that SF3B1 mutations in prolactinoma stimulate PI3K/AKT signaling by downregulating Discs large 1 (DLG1), which was induced by aberrant splicing to enhance tumor invasion and migration." (PMID 35039052, 2022). "N stage, tumor mutational burden (TMB), PIK3CA, and SF3B1 were identified as predictors to build the risk score model." (PMID 35562651, 2022). "These primary mutation events contribute to tumor initiation while subsequence mutations in other genes, such as BAP1, SF3B1, and EIF1AX, contribute to tumor progression and metastasis." (PMID 34706158, 2022). "In examining five key mutations in UM (GNAQ, GNA11, BAP1, SF3B1 and EIF1AX), the xenograft tumours matched the genomic signature of the original patient tumours in 83% of cases." (PMID 34149931, 2021). "Further mechanistic studies identified that the SF3B1 K700E mutation resulted in aberrant splicing of PPP2R5A and led to an increase in c‐Myc expression, which ultimately promoted the Warburg effect and tumor growth in PDAC." (PMID 33932092, 2021). "UM tumors often harbor a tumor-initiating mutation in GNAQ or GNA11 with secondary mutation in EIF1AX, SF3B1, SRSF2, or BAP1 that determines metastatic potential." (PMID 34771666, 2021). "Results revealed that SF3B1 mRNA expression levels were higher in PDAC tumor tissue compared with NTAT." (PMID 34857016, 2021). "Patients are considered medium risk if their tumor is GEP class 1B, T2 or T3 based on AJCC guidelines, or harbors a SF3B1 mutation." (PMID 34771666, 2021). "Mutations in splicing factor 3B subunit 1 (SF3B1) and serine and arginine rich splicing factor 2 (SRSF2) occur in intermediate risk tumours 22,27." (PMID 34149931, 2021). "Knockdown of SF3B1 significantly retarded cell proliferation and tumor growth in a cell line (Panc05.04) with the SF3B1K700E mutation." (PMID 33932092, 2021). "It should be noted that the risk of metastasis highly depends on genetic mutations (BAP1, SF3B1, and EIF1AX) in the tumor." (PMID 34830810, 2021). "All but one tumour have a known UM driver gene mutation (GNAQ, GNA11, BAP1, PLCB4, CYSLTR2, SF3B1, EIF1AX)." (PMID 32415113, 2020).